CYP2B7P (cytochrome P450 family 2 subfamily B member 7, pseudogene )
Synonyms: CYP2B7P1
Gene: Long non-coding RNA gene on chromosome 19 (40,908,423 to 40,950,676, forward strand). Ensembl gene ENSG00000291083.
Diseases named in the same sentence as CYP2B7P in open-access papers:
CYP2B7P is named in the same sentence as 6 diseases in open-access papers, as found by Europe PMC text mining. Sharing a sentence is not in itself a finding about the gene and the disease. The quoted sentences say what the papers report.
Obesity (2 papers, 2020 to 2023). Accumulation of substantial excess body fat. "For instance, target genes (FLAD1, SLFNL1, GNS, FBXL18, CYP2B7P) are commonly upregulated genes in metabolic-induced HCC and are associated with risk factors, such as diabetes, obesity, and other metabolic syndromes." (PMID 32228601, 2020).
diabetes (1 paper, 2020). "CYP2B7P was also found to be a gene target of hsa-miR-183-5p that is a biomarker of HCC and diabetes." (PMID 32228601, 2020).
lung adenocarcinoma (1 paper, 2021). A carcinoma that arises from the lung and is characterized by the presence of malignant glandular epithelial cells. "Lower expression of CYP2B7P is associated with prognosis of lung adenocarcinoma." (PMID 33931030, 2021).
nasopharyngeal carcinoma (1 paper, 2023). A carcinoma arising from the nasopharyngeal epithelium. "Overexpression of CYP2B7P impaired the migration and invasion abilities of nasopharyngeal carcinoma cell lines." (PMID 36975430, 2023). "CYP2B7P is downregulated in nasopharyngeal carcinoma, and its expression is lower in nasopharyngeal carcinoma tissues and cell lines." (PMID 36975430, 2023).
CYP2B7P also shares sentences with these, for which no sentence is quoted: metabolic syndrome (1 paper); rectal tumor (1).